INS (insulin)
Diseases named in the same sentence as INS in open-access papers (continued):
Sharing a sentence is not in itself a finding about the gene and the disease.
Hyperglycemia (continued). "Conversely, sitagliptin, which stimulates insulin secretion, did not improve bone parameters due to ongoing hyperglycemia and the destruction of pancreatic β-cells in the diabetic models studied." (PMID 39723258, 2024). "Of note, it has been suggested that sucrose per se does not affect insulin-glucose uptake, in spite of the fact that rats fed a high-sucrose diet showed mild hyperglycemia." (PMID 38414818, 2024). "Intriguingly, under high-dose STZ challenge, Ghsr-βKO mice exhibited significantly attenuated hyperglycemia, showing improved glucose tolerance and increased insulin secretion in middle-aged and old mice, but not in young mice." (PMID 38794702, 2024). "This vicious cycle continues until β-cell activity can no longer meet the insulin demand in an adequate way, resulting in hyperglycemia." (PMID 39768947, 2024). "However, if the pancreatic beta cells cannot compensate with sufficiently high insulin secretion, this can result in hyperglycaemia and Gestational Diabetes Mellitus (GDM), which is defined by hyperglycaemia with first onset during pregnancy." (PMID 38350951, 2024). "In GDM, β-cell function is decreased, and insulin levels are not able to compensate for increasing insulin resistance, leading to hyperglycaemia." (PMID 39518962, 2024). "In people living with T1DM, due to the complete absence of endogenous insulin production, there is an upregulation of gluconeogenesis and hepatic glycemic output with a consequent tendency to hyperglycemia." (PMID 38542818, 2024). "IAS is a rare cause of hypoglycemia characterized by hyperinsulinemia, positive insulin antibodies, and fluctuations between hyperglycemia and hypoglycemia without the use of insulin." (PMID 39575003, 2024). "The kITT value reflects tissue insulin sensitivity well, as at the 30‐min time point hyperglycemia‐induced counter regulatory hormones have not exerted their action." (PMID 39054559, 2024). "All patients with pre-existing DM and 87% of those without prior DM show evidence of in-hospital hyperglycemia during the immediate post-transplant period, and 66% of those without pre-existing DM have been shown to require insulin upon discharge." (PMID 39451871, 2024). "In a study of 13 cases of patients with non-ketotic hyperglycemia, the combination of anti-epileptics and insulin therapy with proper hydration achieved a seizure-free state in all of the patients, and then anti-epileptics were gradually stopped." (PMID 39077240, 2024). "Glycemic control is also important, although the level of hyperglycemia at which treatment should be initiated (i.e., insulin) is not well established." (PMID 38552059, 2024). "In ZDF rats, during phase II when basal hyperglycemia was restored with GCG-ZDF-BC and INS-ZDF-BC, EGP and TGO tended to reduce progressively by 13% (−Δ 7.3 μmol·kg−1·min−1) and 7% (−Δ 6.6 μmol·kg−1·min−1), respectively, with a slight decrease in the EGP fraction contributing to TGO from 66% to 62%." (PMID 38265288, 2024). "Although Ingersen and colleagues reported a lack of significant changes in insulin sensitivity or secretion, other studies have suggested that ADF has the potential to decrease body weight, lower fasting insulin levels, improve IFG, reduce postprandial hyperglycemia, and decrease levels of HbA1c." (PMID 39203828, 2024). "In HHS, there is a residual amount of insulin secretion that minimises ketosis but does not control hyperglycaemia." (PMID 38907161, 2024). "Unlike non-encapsulated ones, the encapsulated islets maintained insulin secretion and thus reduced hyperglycemia, highlighting the immunoprotective and biocompatible properties of the capsule material." (PMID 39595139, 2024). "Male mice showed no hyperglycemia at 10 or 19 weeks, but at both time-points, global Alms1 KO mice were severely hyperinsulinemic, with insulin concentrations around 10-fold higher than controls." (PMID 38583571, 2024).
Hyperglycemia (continued). "Pretreatment with insulin or metformin did not modify the decreased secretion of IL-1β observed under hyperglycemia, and resulted in a significantly lesser secretion in comparison with the infected placental explants exposed to 10 mM glucose." (PMID 36982317, 2023). "Another mechanism is prolonged hyperglycemia from diet, which can also result in the desensitization of GLUT4 receptors, preventing them from recognizing insulin and rendering the tissues and organs resistant to the effects of insulin." (PMID 38161953, 2023). "Another possibility is that acute hyperglycaemia does not affect microvascular reactivity in subjects with higher glucose tolerance (i.e., higher insulin sensitivity)." (PMID 38255671, 2023). "While BL6 mice were resistant to fasting hyperglycaemia, hyperinsulinaemia and glucose-induced insulin secretion, with no change in the HOMA-IR, they exhibited mild impairments in glucose tolerance and insulin sensitivity." (PMID 36949095, 2023). "It results in a significant lack of insulin production by the pancreas and the ensuing hyperglycemia, which needs to be regulated through a tailored administration of insulin throughout the day." (PMID 36976069, 2023). "Traditionally, most of these patients are given subcutaneous bolus insulin to treat hyperglycaemia, often with a non-optimal glycaemic control during the 1st postoperative days." (PMID 37540239, 2023). "Similarly, mice with global Serca2 heterozygosity exhibit hyperglycemia in response to HFD owing to impaired insulin biosynthesis and secretion, but have normal adiposity and insulin sensitivity." (PMID 36823211, 2023). "The reduction in insulin and IGF1 signaling, leading to a decline in the ICC and subsequent myopathy, has been identified as a key contributor to diabetic gastroparesis, distinct from the effects of hyperglycemia." (PMID 37759758, 2023). "Twenty-one (55.3%) infants included in the study did not receive insulin, and seventeen (44.7%) had hyperglycemia and were treated with insulin." (PMID 37892314, 2023). "For example, berberine did not alter insulin secretion under low or normal glucose conditions, but was effective in subjects with hyperglycemia." (PMID 37513825, 2023). "While the results from Groups 2 and 4 from the present study appear consistent mechanistically with nonpregnant individuals, we did not identify abnormal insulin sensitivity or secretion in Group 3 (postprandial hyperglycemia group)." (PMID 36950879, 2023). "Summarize, we suggest that hyperglycemia is not the single necessary for generation of insulin+ cells in liver." (PMID 38019818, 2023). "Unexpectedly, women with isolated postload hyperglycemia appeared to have comparable insulin secretion and sensitivity as the women without GDM." (PMID 36950879, 2023). "According to the SITC (2017), type 1 diabetes patients without DKA should stop ICIs treatment when hyperglycemia ≥ grade 3 occurs and should be treated with insulin until recovery to grade 1 is achieved." (PMID 37554766, 2023). "The association of the rs1111875 recessive genotype with dyslipidemia and hyperglycemia in our study suggests the SNP affects insulin sensitivity rather than insulin secretion pathways." (PMID 37816730, 2023). "Using the same animal model but with access to a diet supplemented with bread, we did not notice significant changes in insulin levels, despite the observed hyperglycemia, 5 weeks after STZ injection." (PMID 37106960, 2023). "Studies on the natural history of T2DM have documented that hyperglycemia develops once insulin secretion is no longer adequate for the metabolic state." (PMID 37522521, 2023). "This metabolic disorder affects insulin-producing β cells in the pancreas, leading to a profound lack of insulin and subsequent hyperglycemia." (PMID 37048770, 2023). "The acylated ghrelin shows hyperglycaemic effects leading to IR, while non-acylated ghrelin contrasts hyperglycaemia and improves insulin sensitivity." (PMID 38136211, 2023).
Hyperglycemia (continued). "Talin-1 defficiency in β-cells leads to hyperglycemia in mice upon glucose challenge, which is primarily attributed to impaired glucose-stimulated insulin secretion (GSIS) and reduced β-cell mass, rather than peripheral insulin resistance." (PMID 37903776, 2023). "During the progression into the diabetic state, insulin follows a nonmonotonic time course (magenta), whereas glucose levels progressively increase (magenta), and hyperglycemia concurrently exists with hyperinsulinemia for several years." (PMID 38026205, 2023). "However, given that insulin secretory defects seem to exist early on, even before the development of glucose abnormalities, and fasting hyperglycemia is atypical in TS, this drug may be a less appropriate first-line hyperglycemia treatment for individuals with TS." (PMID 36875465, 2023). "No insulin-induced effects on the expression of the remaining genes were observed during hyperglycemia (FCHG, ins = 0.93–1.20)." (PMID 37313172, 2023). "Out of the 16 patients experiencing hyperglycemia, three did not require hypoglycemic therapy, two temporarily used insulin (both in the 8 mg QD group), and 11 were treated with oral hypoglycemic agents, achieving subsequent glucose control." (PMID 38037839, 2023). "We examined time to CFRD diagnosis based on OGTT results; however, we did not capture CFRD diagnoses by other methods including hyperglycemia during hospitalizations or other indications for insulin start." (PMID 40303238, 2023). "Lack of thiamine in insulin‐producing cells can lead to hyperglycemia (nontype 1 diabetes), and thiamine is required by pancreatic B‐cells for glucose transport across the cell membrane, physiological consumption, and insulin secretion." (PMID 37091967, 2023). "She developed severe nausea, tachycardia, tachypnea, and hyperglycemia, leading to ketoacidosis within 15 hours of receiving the second dose of the mRNA Moderna vaccine, which did not resolve with multiple boluses of insulin." (PMID 38022276, 2023). "It is well known that when patients have elevated blood glucose and need to increase insulin administration, CVII is rapidly absorbed, and with the same dosage of insulin, CVII can control hyperglycemia faster than other regimens, so the insulin dosage is relatively low." (PMID 37674887, 2023). "Most participants stated that despite being on insulin therapy hypoglycaemia was not common and hyperglycaemia was the predominant issue." (PMID 38066492, 2023). "In contrast, while FVB mice did not develop hyperglycaemia, they showed substantial glucose intolerance, hyperinsulinaemia and increased glucose-induced insulin secretion." (PMID 36949095, 2023). "Sodium–glucose co-transporter 2 inhibitors (SGLT2i) reduce hyperglycaemia by promoting the urinary excretion of glucose and not involving insulin secretion." (PMID 36983739, 2023). "Glucose is primarily taken up by skeletal muscle, and during hyperglycemia, all non-insulin mediated glucose uptake and 75–95% of insulin mediated glucose uptake occurs in skeletal muscle." (PMID 37311899, 2023). "Likely in anticipation of the planned PA session, the participant used no insulin bolus for the preceding meal and commenced the session in hyperglycemia." (PMID 36791144, 2023). "Regular consumption of chilli-containing foods has been reported to reduce hyperglycaemia and hyperinsulinemia with no impact on fasting plasma glucose and insulin levels in healthy individuals." (PMID 36985831, 2023). "In contrast, postprandial hyperglycemia in post-gastrectomy patients has also been reported to be due to decreased insulin secretion rather than increased insulin resistance." (PMID 37084095, 2023). "In contrast, T2DM is a chronic condition that occurs when body cells do not respond to insulin, renowned as “insulin resistance” thereby resulting in hyperglycemia." (PMID 36756113, 2023).
Hyperglycemia (continued). "CSII intervention was consistent with the characteristics of physiological insulin secretion, resulting in a lower MBG, while the incidence of hyperglycemia (>180 mg/dL) was higher than that of CVII; therefore, the incidence of SSI was essentially comparable and lower in both methods." (PMID 37674887, 2023). "The streptozotocin–nicotinamide animal model is characterized by mild non-fasting hyperglycemia and slightly decreased insulin levels, as also shown in our study." (PMID 36837509, 2023). "In the absence of appropriate insulin adjustment, this manifests clinically as late sustained postprandial hyperglycemia." (PMID 38057844, 2023). "The metabolism of ketone bodies mitigates some of the negative CNS effects of hyperglycemia, thereby improving insulin sensitivity and attenuating insulin resistance." (PMID 37415915, 2023). "With time, beta-cells become exhausted and cannot compensate for the increased insulin demand, leading to hyperglycemia while insulin values revert to inadequately normal and only later reduced levels." (PMID 36895000, 2023). "The model predicts both the transient and steady-state profiles of secreted insulin and glucagon, including the typical biphasic response of normal β-cells to hyperglycemia." (PMID 37645413, 2023). "In the present study, it was also found that Postn-null mice did not have hyperglycemia because they exhibited preserved insulin secretory function even after STZ injections compared with WT mice." (PMID 37845302, 2023). "This study found that poor glycemic control was associated with being female, aged younger, receiving a combination of oral hypoglycemic agents and insulin, not taking biguanide, and the presence of hyperglycemia and comorbid diseases." (PMID 37638377, 2023). "This unexpected finding suggests that indices of insulin secretion and sensitivity do not distinguish women with postload hyperglycemia from euglycemic women and that alternative pathological mechanisms should be considered." (PMID 36950879, 2023). "Insulin binds to insulin receptors to activate the PI3K/Akt signaling pathway, which plays a vital role in glucose transporter 4 (GLUT4) traveling to the cell surface that ultimately reduces hyperglycemia." (PMID 36831708, 2023). "On the other hand, short-term corticosteroid treatment probably does not influence insulin secretion which determined hyperglycemia in the current study." (PMID 37460458, 2023). "Much-lower-quality studies using insulin to treat hyperglycaemia provide much-lower-quality evidence, not least because of large variations in treatment thresholds, protocols, and monitoring." (PMID 38004135, 2023). "This is different to ‘classical’ diabetic ketoacidosis observed in type 1 diabetes, where inadequate insulin treatment fails to suppress both ketogenesis and blood glucose levels (leading to hyperglycaemia and profound dehydration)." (PMID 37159343, 2023). "Because of the lack of insulin treatment in the present study, the animals were under persistent hyperglycemia, but the level of the βHB remained unchanged." (PMID 36650229, 2023). "Diabetes, a chronic disease characterized by hyperglycemia, occurs due to insulin resistance or the lack of production of insulin." (PMID 37570730, 2023). "GDM develops when a woman’s pancreas fails to secrete enough insulin in response to significantly decreased insulin sensitivity, resulting in varying degrees of hyperglycemia." (PMID 37432359, 2023). "Treatment of maternal hyperglycaemia is also dependent on the fetal genotype, with insulin treatment not being necessary or desirable when the fetus has inherited the GCK variant and is predicted to be of normal birthweight." (PMID 37653058, 2023).
Hyperglycemia (continued). "These mice do not develop hyperglycemia or reduced plasma insulin levels, which are observed in Akita+/− mice in either fed or fasted states." (PMID 37628845, 2023). "When insulin overproduction can no longer compensate for IR, hyperglycemia becomes clinically significant." (PMID 38066741, 2023). "Furthermore, by improving insulin-stimulated surface translocation of GLUT4 in cardiomyocytes, AAV9-cBIN1 helped rescue hyperglycemia in db/db mice." (PMID 37639557, 2023). "Produced by glucose injections hyperglycemia in non-diabetic or diabetic mice led to the appearance of proinsulin- and insulin-positive cells in liver, adipose tissue and bone marrow within 3 days." (PMID 38019818, 2023). "For the patient's history of steroid‐induced hyperglycemia, glucose levels were monitored closely during hospitalization, and the patient did not require insulin." (PMID 37255617, 2023). "Subcutaneous insulin injections failed to control the patients' hyperglycemia, requiring up to 1.83 and 1.81 units/kg/day of intravenous insulin, respectively." (PMID 38022370, 2023). "Apart from the patient with hyperglycemia on insulin treatment, none of the patients required admission for treatment of adverse events, and all were managed in an outpatient setting." (PMID 37380669, 2023). "This study reported the treatment of hyperglycemia using herbal medicines without oral hypoglycemic agents or insulin therapy." (PMID 38003968, 2023). "It is characterized by low or absent insulin levels in the blood, leading to severe hyperglycemia in the patient, which requires temporary insulin therapy in around 50% of cases or permanent insulin therapy in other cases." (PMID 37443665, 2023). "Type 1 diabetes, also known as juvenile diabetes or insulin-dependent diabetes, is a chronic autoimmune condition in which the pancreas makes little or no insulin leading to resultant hyperglycemia." (PMID 37663700, 2023). "Surgery sparks a cascade of metabolic, endocrine, and hemodynamic responses in the body which can contribute to insulin resistance, protein breakdown, and gluconeogenesis, resulting in hyperglycemia and a negative nitrogen balance." (PMID 38013300, 2023). "Nutrient intake and biochemical monitoring data confirmed that protein/energy ratios were maintained in the SCAMP intervention group without increasing the incidence of hyperglycaemia, insulin treatment, or the derangement of plasma mineral/electrolyte levels." (PMID 38004135, 2023). "The most common manifestation of this disease is hyperglycemia, which is due to the absolute or relative lack of insulin or the inability of cells to respond to insulin production." (PMID 37509511, 2023). "In an attempt to understand the effects of IR on stroke recovery, independently of hyperglycemia, we took advantage of mouse models of early IR/decreased insulin sensitivity with or without concurrent hyperglycemia." (PMID 36835405, 2023). "A total of 2.9% (3/103) of children had mild fasting hyperglycaemia (> 5.6 mmol/L) and normal fasting plasma insulin levels, but none of these children had been exposed to prednisone in utero." (PMID 36040672, 2023). "A deficiency in glucose-stimulated insulin secretion (GSIS) is an early manifestation of T2DM; consequently, hyperglycemia is not solely responsible for β-cell exhaustion." (PMID 37188647, 2023). "Sensitivity to insulin after surgery is significantly decreased when insulin is not used intraoperatively to treat hyperglycemia." (PMID 36310325, 2023). "Although diet control and exercise could partly alleviate hyperglycemia, almost all T2DM patients still need antidiabetic drugs and/or insulin to maintain standard blood glucose." (PMID 37303813, 2023). "We also showed that prolonged low-dose TCDD exposure (20 ng/kg/day, 2×/week) accelerated high-fat diet (HFD)-induced hyperglycemia and impaired glucose-induced plasma insulin levels in adult female but not male mice." (PMID 37115651, 2023).